NDUFB2 (NADH:ubiquinone oxidoreductase subunit B2)
Description:
Accessory subunit of the mitochondrial membrane respiratory chain NADH dehydrogenase (Complex I), that is believed not to be involved in catalysis. Complex I functions in the transfer of electrons from NADH to the respiratory chain. The immediate electron acceptor for the enzyme is believed to be ubiquinone.
Synonyms: CI-AGGG; AGGG
Tractability: Small molecule: an approved drug acts on it; a structure with a bound ligand is known. Antibody: UniProt places it where antibodies can reach, with high confidence.
Gene: Protein-coding gene on chromosome 7 (140,690,777 to 140,723,923, forward strand). Ensembl gene ENSG00000090266.
Subcellular location: Mitochondrion inner membrane
Subcellular location (Human Protein Atlas): Nucleoplasm; Mitochondria
Pathways (Reactome):
Metabolism: Complex I biogenesis; Respiratory electron transport
Gene Ontology:
Molecular function: NADH dehydrogenase (ubiquinone) activity
Biological process: aerobic respiration; mitochondrial electron transport, NADH to ubiquinone; proton motive force-driven mitochondrial ATP synthesis; proton transmembrane transport
Cellular component: mitochondrial inner membrane; mitochondrion; respiratory chain complex I
Genetic constraint (gnomAD): Loss-of-function variants: 13 observed, 13.41 expected, observed/expected ratio (o/e) 0.97, 90% interval 0.63 to 1.53. The upper end of that interval is the gene's LOEUF score, 1.53, which puts it in group 6 of 6, group 1 being the genes least tolerant of losing a copy. Missense variants: 150 observed, 140.51 expected, observed/expected ratio (o/e) 1.07, 90% interval 0.93 to 1.22. Synonymous variants: 46 observed, 49.58 expected, observed/expected ratio (o/e) 0.93, 90% interval 0.73 to 1.19.
Homologues: Orthologues: chimpanzee NDUFB2 (99% identical), chimpanzee NDUFB2 (98% identical), macaque NDUFB2 (91% identical), dog NDUFB2 (85% identical), mouse Ndufb2 (83% identical), rat Ndufb2 (76% identical), rabbit NDUFB2 (74% identical), guinea pig NDUFB2 (72% identical), pig NDUFB2 (66% identical), tropical clawed frog ndufb2 (60% identical), rat Ndufb2 (59% identical), zebrafish ndufb2 (47% identical), and 1 more.
Diseases named in the same sentence as NDUFB2 in open-access papers:
NDUFB2 is named in the same sentence as 22 diseases in open-access papers, as found by Europe PMC text mining. Sharing a sentence is not in itself a finding about the gene and the disease. The quoted sentences say what the papers report.
Parkinson disease (3 papers, 2013 to 2021). A progressive degenerative disorder of the central nervous system characterized by loss of dopamine producing neurons in the substantia nigra and the presence of Lewy bodies in the substantia nigra and locus coeruleus. "This analysis revealed that the genes implicated in Parkinson’s disease (Atp5a1, Ndufa7, Ndufb2, Ndufs8, Park7, Cox7a2, Cox7c, Cox6b1, Cycs, Uchl1) were upregulated in thia-exposed mice (p-value = 4.2E-3)." (PMID 34295895, 2021).
Alzheimer disease (2 papers, 2021). A progressive, neurodegenerative disease characterized by loss of function and death of nerve cells in several areas of the brain leading to loss of cognitive function such as memory and language. "Ndufb2 is part of the mitochondrial respiratory chain complex I assembly and has been implicated previously in bacterial sepsis and Alzheimer’s disease, suggesting that it may play a role in inflammation." (PMID 34566577, 2021).
breast carcinoma (1 paper, 2020). "The top significant pathway, ubiquinone metabolism pathway, was enriched in the positively correlated blue module of 5P_tRNA-Leu-CAA-4-1, where high expression of NDUFB2 had a better prognostic value in breast cancer patients." (PMID 32785169, 2020). "Genes such as NDUFB1, NDUFB2, and NDUFB7 were found to have significant prognostic values for breast cancer patients." (PMID 32785169, 2020).
glioma (1 paper, 2023). A benign or malignant brain and spinal cord tumor that arises from glial cells (astrocytes, oligodendrocytes, ependymal cells). "Furthermore, as for the survival status, consistently, we found that the expression of NDUFB2 is negatively associated with the survival status in glioma (P = 0.0084)." (PMID 36860730, 2023). "Among the 10 prognosis-related necroptosis genes, we found that only NDUFB2 is highly increased in the glioma and statistically correlated with the overall survival in GBM." (PMID 36860730, 2023). "The heat map shows higher expression of NDUFB2 list in the high-grade glioma, classical subtype, and IDH-1 wild-type groups, and the trend is similar is other related genes." (PMID 36860730, 2023).
hepatocellular carcinoma (1 paper, 2025). A malignant tumor that arises from hepatocytes. "Previous studies have shown that QKI binds upstream and downstream of SMARCA5, ZEB1 and NDUFB2 RNA to promote circRNA formation in lung cancer, prostate cancer, and hepatocellular carcinoma." (PMID 40263288, 2025).
Huntington disease (1 paper, 2012). Huntington disease (HD) is a rare neurodegenerative disorder of the central nervous system characterized by unwanted choreatic movements, behavioral and psychiatric disturbances and dementia. "For example: Huntington’s disease (NDUFA7, NDUFC1, NDUFB2, NDUFB3, NDUFA8), atrophy of optic nerve (NDUFS4) and Leigh syndrome (NDUFS7, NDUFA2, NDUFS4)." (PMID 23028713, 2012).
hypertrophic cardiomyopathy (1 paper, 2024). A condition in which the myocardium is hypertrophied without an obvious cause. "NDUFB1 and NDUFB2 are associated with altered cardiac energetics and mitochondrial dysfunction in patients with hypertrophic cardiomyopathy, and ROMO1 is an essential redox-dependent regulator of mitochondrial dynamics." (PMID 38396938, 2024).
low grade glioma (1 paper, 2023). A grade I or grade II glioma arising from the central nervous system. "The main function of NDUFB2 is further explored by a web tool and showed that it is related to DNA repair, stemness, and cell cycle, and the role of NDUFB2 might be different in low-grade glioma (LGG) and GBM." (PMID 36860730, 2023).
non-small cell lung carcinoma (1 paper, 2022). A group of at least three distinct histological types of lung cancer, including non-small cell squamous cell carcinoma, adenocarcinoma, and large cell carcinoma. "In this context, it was shown that circNDUFB2, generated from exons 2 and 3 of the NADH:ubiquinone oxidoreductase subunit B2 (NDUFB2) gene, impaired non-small-cell lung cancer progression by promoting the degradation of the oncogenic insulin-like growth factor 2 mRNA-binding proteins (IGF2BPs)." (PMID 35269953, 2022).
tumor (2 papers, 2023 to 2025). "Importantly, however, the interrogation of the DEPC 3.0 database showed that nearly all of the identified proteins, with the exception of only three (COX16, NDUFB2, COX8C), are consistently annotated as being altered during tumor dissemination and metastatic progression." (PMID 41157129, 2025). "However, the role of NDUFB2 in tumor, especially in GBM, is not extensively investigated." (PMID 36860730, 2023).
cancer (1 paper, 2022). A tumor composed of atypical neoplastic, often pleomorphic cells that invade other tissues. "In addation, CAT, POLE, NTHL1, ATP7B, ISCA2, NDUFA1 and NDUFB2 have also been reported to play a key role in the development of cancers." (PMID 36685880, 2022).
neurodegenerative disease (1 paper, 2013). A disorder of the central nervous system characterized by gradual and progressive loss of neural tissue and neurologic function. "Results on metabolic pathways support an alteration of the Neurodegenerative Diseases and Nervous system C2 classes with the most frequently associated differentially expressed genes in the BSP (BAD, NEFH, NDUFB2, DERL1, NEFL)." (PMID 23782433, 2013).
NDUFB2 also shares sentences with these, for which no sentence is quoted: bacterial sepsis (2 papers); amyotrophic lateral sclerosis (1); cardiac hypertrophy (1); influenza infection (1); Leigh syndrome (1); lung carcinoma (1); prostate carcinoma (1); Sepsis (1); thyroid cancer (1); thyroiditis (1).